PRNCR1 (prostate cancer associated non-coding RNA 1)
Diseases named in the same sentence as PRNCR1 in open-access papers (continued):
Sharing a sentence is not in itself a finding about the gene and the disease.
cancer (29 papers, 2014 to 2025). A tumor composed of atypical neoplastic, often pleomorphic cells that invade other tissues. "(V) Looping enhancers and regulating genome organization; for instance, prostate cancer-associated noncoding RNA 1 (PRNCR1) and prostate-specific transcript (PCGEM1) are two lncRNAs that increase the enhancer-promoter looping in cancer cells." (PMID 35359941, 2022). "Prostate cancer-associated non-coding RNA 1 (PRNCR1) is a lncRNA that has been proposed to contribute to prostate carcinogenesis by increasing the looping of androgen receptor (AR)-bound enhancers to AR target genes and, in turn, increasing cell proliferation." (PMID 33374332, 2020). "We selected five PRNCR1 SNPs: rs1016343, rs13252298, rs7841060, rs16901946, and rs1456315, which have been previously associated with cancer." (PMID 31288430, 2019). "A meta-analysis study showed among the PRNCR1 rs13252298 genotypes, the G/A homozygous variant is associated with cancer." (PMID 31487296, 2019). "In order to comprehensively evaluate the precise effect of PRNCR1 rs1016343 on cancer risk, we performed a meta-analysis to summarize all published studies." (PMID 28159929, 2017). "For PRNCR1, studies mainly reported the relationship of rs1016343 (n = 7), rs13252298 (n = 4), rs7007694 (n = 3), rs16901946 (n = 3), rs1456315 (n = 3) and cancer risk." (PMID 28159929, 2017). "Herein, we also evaluated the association of PRNCR1 rs13252298, rs7007694, rs16901946 and rs1456315 and cancer risk in this meta-analysis." (PMID 28159929, 2017). "For example, metastasis-associated lung adenocarcinoma transcript 1 (MALAT1), prostate cancer associated non-coding RNA 1 (PRNCR1), prostate cancer gene expression marker 1 (PCGEM1), H19, and several new lncRNAs involve in glioma development." (PMID 26172293, 2015). "This is demonstrated by the sequential assembly of Prostate cancer associated non-coding RNA 1 (PRNCR1) and lncRNA prostate cancer gene expression marker 1 (PCGEM1) with the androgen receptor (AR), the MEG3 structure required for its tumor suppressive function." (PMID 34504983, 2021). "The PRNCR1 catalytic subunit has been widely linked to cancer development." (PMID 31487296, 2019). "Recent findings recommended that people with PRNCR1 variants may have a higher risk of developing cancer." (PMID 31487296, 2019). "This is the first study to report PRNCR1 variant association with cancer in a Saudi population." (PMID 31487296, 2019). "Recently, PRNCR1 genomic variants were identified to be associated with increased cancer risk." (PMID 31487296, 2019). "Amongst the five PRNCR1 SNPs included in our study, rs16901946 G/A, rs13252298 G/A, rs1016343 T/C, and rs1456315 G/A could be predictive biomarkers of cancer risk." (PMID 29802154, 2018). "Moreover, four prostate cancer-associated ncRNA 1 (PRNCR1, rs16901946 G/A, rs13252298 G/A, rs1016343 T/C, and rs1456315 G/A) SNPs were in association with cancer risk." (PMID 29802154, 2018). "Moreover, lncRNA PRNCR1 SNPs were observed to be risk of diverse cancers." (PMID 29802154, 2018). "Besides, we also investigated the effect of lncRNA PRNCR1 on cancer risk." (PMID 28159929, 2017). "High expression of lncRNA prostate cancer non-coding RNA 1 (PRNCR1) leads to significant overexpression of MTDH through sponging miR-126-5p to promote the proliferation of cancer cells." (PMID 38152110, 2023). "Among the ceRNAs of miR-944, highly expressed circSERPINA3, circHAS2, SNHG6, and PRNCR1 can be used as biomarkers for poor clinicopathological features and poor prognosis in cancer patients." (PMID 36077769, 2022). "miR-944 can participate in three signaling axes to promote cancer cell apoptosis, including the PRNCR1/miR-944/HOXB5, CircCSPP1/miR-944/FZD7, and CircFUT8/miR-944/YES1 signaling axes." (PMID 36077769, 2022). "The upregulation of PCAT1, PRNCR1, PVT1, and MYC potentially confers the risk of cancer as their upregulation is strongly associated with prostate cancer." (PMID 32680982, 2020).
cancer (continued). "Although several studies have revealed that lncRNAs on 8q24, including PRNCR1, CCAT2 and PCAT1, encompass the cancer predisposition SNPs, the prognostic significance of these lncRNAs in GC patients has not yet been fully explored." (PMID 32117633, 2020). "Herein, we conducted a meta-analysis to summarize all eligible case-control studies to evaluate the overall cancer risk and common lncRNAs (HOTAIR, PRNCR1, H19, and POLR2E) polymorphisms." (PMID 28159929, 2017). "Our meta-analysis results revealed that these four lncRNAs polymorphisms (HOTAIR rs920778, PRNCR1 rs1016343 and rs16901946, POLR2E rs3787016) can contribute to cancer risk." (PMID 28159929, 2017). "For PRNCR1 (rs1016343, rs16901946) and POLR2E (rs3787016), we also found the significant association with incresed risk of cancer (all P<0.05)." (PMID 28159929, 2017). "In these 38 included articles, we observed that a variety of lncRNA genes had been investigated the association with cancer risk, among which lncRNA HOTAIR, PRNCR1, H19, and POLR2E had been widely studied." (PMID 28159929, 2017). "We performed a meta-analysis to summarize the results of common lncRNAs (HOTAIR, PRNCR1, POLR2E and H19) polymorphisms on cancer risk, by using the random-effect model to obtain the odds ratio (ORs) and 95% confidence interval (95%CI)." (PMID 28159929, 2017). "In conclusion, our meta-analysis showed that lncRNA HOTAIR rs920778, PRNCR1 rs1016343 and rs16901946, POLR2E rs3787016 were associated with cancer susceptibility." (PMID 28159929, 2017). "The results indicate that these four lncRNAs polymorphisms (HOTAIR rs920778, PRNCR1 rs1016343 and rs16901946, POLR2E rs3787016) can contribute to the increased risk of cancer." (PMID 28159929, 2017). "We found a borderline decrease in PRNCR1 expression in metastatic castrate-resistant cancer (p = 0.047, Student's t-test)." (PMID 24727738, 2014). "Previous studies of PRNCR1 have mainly focused on its role in cancers." (PMID 35422021, 2022). "Accumulating evidence suggested that prostate cancer non-coding RNA 1 (PRNCR1) participated in the pathogenesis of NSCLC, whereas the elaborate mechanism remains unclear." (PMID 31912882, 2020). "Long noncoding RNA PRNCR1 is downregulated in many types of cancer." (PMID 31487296, 2019). "Recent studies demonstrated that PRNCR1 plays a critical role in progression of several cancers." (PMID 31487296, 2019). "Recent studies demonstrated that PRNCR1 plays a vital role in cancer progression." (PMID 31487296, 2019). "Therefore, we included a larger size of cancer patients with more SNPs of lncRNA PRNCR1 into our study to confirm the results." (PMID 29802154, 2018). "Thus, in the meta-analysis, we mainly focus on evaluating the association between HOTAIR, PRNCR1, H19, POLR2E polymorphisms and cancer risk." (PMID 28159929, 2017). "Additionally, for the PRNCR1 rs1016343, cancer type (P <0.001) was observed to contribute to substantial heterogeneity (95% of the Tau-squared)." (PMID 28159929, 2017). "The pooled OR and stratified analyses showed that amongst the five PRNCR1 SNPs included in the meta-analysis, only rs16901946 G/A, rs13252298 G/A, rs1016343 T/C, and rs1456315 G/A were associated with cancer risk, while the association of the rs7007694 C/T was not statistically significant (P>0.05)." (PMID 29802154, 2018). "Some lncRNAs, such as Prostate cancer non-coding RNA 1 (PRNCR1), HOTAIR, and UCA1, are believed to be involved in cancer development." (PMID 31487296, 2019). "Here we selected six candidate cancer-related lncRNAs (ZFAS1, PRNCR1, GAS5, TUG1, linc-ROR, and H19) through articles that were previously reported to be dysregulated in cancer." (PMID 29559565, 2018). "Through searching the published literatures, six lncRNAs (ZFAS1, PRNCR1, GAS5, TUG1, linc-ROR, H19) which have been reported to be abnormally expressed in cancer were included in the present study." (PMID 29559565, 2018).
cancer (continued). "This research also showed that PRNCR1 silencing could enhance cell apoptosis, block proliferation, migration, invasion, and EMT, of which EMT served an essential role in cancer progression." (PMID 31912882, 2020). "Finally, while PCGEM1 is upregulated in cancer patients from matched tumor/benign samples, PRNCR1 does not convincingly exhibit this pattern of upregulation." (PMID 24727738, 2014). "PRNCR1 is situated in a sensitive region of the genomic area for CRC, yet the role of PRNCR1 is still not yet studied in Saudi populations for any cancer." (PMID 31487296, 2019).
tumor (10 papers, 2017 to 2025). "In TSCC, high expression of PRNCR1 was negatively correlated with miR-944 and was significantly associated with larger tumor size, later clinical stage, more lymph node metastasis, and shorter OS." (PMID 36077769, 2022). "To check the association of PRNCR1 SNPs with age, gender, and tumor location of the patients, we did a further stratified analysis." (PMID 31487296, 2019). "The association of PRNCR1 SNPs with CRC was also analyzed by stratifying the tumor samples based on tumor location." (PMID 31487296, 2019). "In NSCLC, lncRNA PRNCR1 upregulates HEY2 promoting tumour progression by competitively binding miR-448." (PMID 32564237, 2020). "We further analyzed the impact of PRNCR1 polymorphisms on GC risk in combination with various characteristics and clinical features, including age, sex, tumor differentiation, histologic type, T classification, lymph node metastasis (LNM), and tumor stage." (PMID 31288430, 2019). "Interestingly, two of the DE lncRNAs (lncRNA_1086.1 and lncRNA_2340.1) were homologous with the human PRNCR1 and HOXA-AS3 lncRNAs that act as oncogenes or tumor suppressors, respectively." (PMID 40538732, 2025).
PRNCR1 also shares sentences with these, for which no sentence is quoted: prostatic intraepithelial neoplasia (3 papers); breast carcinoma (2); non-small cell lung carcinoma (2); cervical cancer (1); diabetes (1); esophageal cancer (1); hepatocellular carcinoma (1); kidney damage (1); liver cancer (1); lung carcinoma (1); melanoma (1); meningioma (1); metastasis (1); pancreatic carcinoma (1); prostate (1); type 1 diabetes (1).